INS (insulin)
Diseases named in the same sentence as INS in open-access papers (continued):
Sharing a sentence is not in itself a finding about the gene and the disease.
Obesity (continued). "The reduction of SCFAs may play an important role in reducing insulin sensitivity and the occurrence of obesity." (PMID 40384781, 2025). "Cluster 1 (Red): This group focuses on the mechanisms of macrophage involvement in non-alcoholic fatty liver disease (NAFLD), including keywords such as adipose tissue, inflammation, insulin resistance, macrophage polarization, metabolism, obesity, progression, and recruitment." (PMID 40406489, 2025). "Additionally, it was also closely associated with several circulating parameters (i.e., glucose, insulin, triglycerides, leptin) in diet-induced obesity (DIO) mice." (PMID 40298780, 2025). "Researchers have studied almond shells, which are rich in polyphenol compounds that may lower lipid levels, for their potential to modulate insulin sensitivity and combat obesity." (PMID 41303557, 2025). "However, in insulin-resistant individuals with obesity, GLUT-2 is known to accumulate in the apical membrane, allowing glucose to passively diffuse into the bloodstream." (PMID 40628708, 2025). "These increased risks might be due to elevated estrogen levels that occur from enhanced aromatization in the adipose tissue and increases in the levels of mitogenic agents such as INS and/or IGF associated with obesity-related metabolic syndromes (DM and BC)." (PMID 41221514, 2025). "Increased systemic TNF-α in obesity leads to increased activity of IKK, p38 MAPK, JNK, and PKC proteins, which modify IRS protein serine residues and hinder tyrosine phosphorylation, causing insulin resistance in adipose tissues, muscles, and the liver." (PMID 40141412, 2025). "The fact that peak LH levels were lower as the degree of obesity increased, even though E2 levels remained unchanged, suggested mechanisms such as insulin and leptin resistance, decreased SHBG, and elevated androgen levels in obese individuals, independent of sex steroids." (PMID 40095159, 2025). "These subtypes may achieve improved glycemic control by combining lifestyle and pharmacologic approaches that improve insulin sensitivity and mitigate obesity." (PMID 41212558, 2025). "A study on AR knockout (ARKO) female mice showed increased body weight, elevated hepatic triglyceride, reduced insulin sensitivity, and higher plasma cholesterol levels, suggesting a protective role of AR against diet-induced obesity and dyslipidemia in females." (PMID 41438090, 2025). "We have demonstrated enhanced metabolic protection in male SNAP25Δ3/Δ3 mice housed at room temperature (22°C), including increased adipose tissue beiging and glucose uptake and enhanced insulin sensitivity, rendering them resistant to diet-induced obesity (DIO)." (PMID 40176888, 2025). "Therefore, we propose rutin as a bioactive component based on the LC-MS and HPLC chromatograms from this study, along with the results regarding the effects of RFE on obesity and insulin sensitivity." (PMID 40076460, 2025). "Studies have shown that a combination of resistance and aerobic exercise is of particular interest, as it provides greater benefits than aerobic exercise or resistance exercise alone, in adolescents with obesity, by improving fasting glucose, insulin, and insulin resistance levels." (PMID 40868462, 2025). "We next examined whether Fam20c influences insulin signaling in peripheral tissues during early obesity." (PMID 41148235, 2025). "Understanding insulin signaling pathways in the brain could open new therapeutic avenues for conditions like Alzheimer’s disease and obesity." (PMID 40725728, 2025). "Adipocytes, adipose tissue macrophages (ATMs), hepatocytes, and insulin-sensitive tissues exhibit distinct iron-handling characteristics that collectively shape tissue-specific outcomes of inflammation, ferroptosis, and insulin resistance in obesity and T2D." (PMID 40943225, 2025).
Obesity (continued). "Thus, rapid muscular glucose clearance, improved insulin sensitivity, and anti-inflammatory signaling likely converge to produce the acute metabolic benefits observed—particularly pronounced in obesity." (PMID 41356824, 2025). "In particular, a dietary pattern rich in high energy and saturated fat intake promotes overweight or obesity by accelerating lipid absorption; nevertheless, a low saturated fat intake for 2 years improves insulin sensitivity in children with a family history of obesity." (PMID 40979562, 2025). "The mechanisms that link obesity and cancer include the elevated levels of insulin, which can promote carcinogenesis, either directly through insulin receptors or indirectly by lowering IGF-binding proteins and increasing circulating IGF-1 levels, which in turn act on cancer cell receptors." (PMID 40364176, 2025). "Furthermore, obesity disrupts the balance of leptin and adiponectin, two key adipokines involved in energy homeostasis and insulin sensitivity." (PMID 40429763, 2025). "This indicates that RFE can improve obesity-induced glucose intolerance and insulin sensitivity." (PMID 40076460, 2025). "Recently, the carbohydrate–insulin model of obesity has gained more and more supporters." (PMID 40277805, 2025). "Obesity itself may be both a contributor to and a consequence of cardiovascular remodeling, particularly when coupled with insulin resistance and chronic inflammation." (PMID 40710036, 2025). "Additionally, SCFAs improve insulin sensitivity and glucose homeostasis, processes that are often disrupted in individuals with obesity." (PMID 40278284, 2025). "However, there is a positive correlation between insulin insensitivity and obesity, and in children with T1D, an increased BMI was found in the first year of life, while the prevalence and titer of GADA are associated with BMI in FDRs." (PMID 40004639, 2025). "Furthermore, mice with fat specific ablation of the A2AR exposed to a diet rich in fat showed increased propensity to obesity, decreased insulin sensitivity, elevated adipose tissue inflammation, and hepato-steatosis and hepato-steatitis." (PMID 39828097, 2025). "Adiponectin, which is typically reduced in obesity, enhances insulin sensitivity, suppresses reactive oxygen species, and modulates anti-inflammatory pathways via AMP-activated protein kinase (AMPK) and peroxisome proliferator-activated receptor (PPAR) pathways." (PMID 41155642, 2025). "Mechanistically, obesity exacerbates tumor progression through hormonal imbalance, chronic inflammation, and adipokine and insulin signaling, targets that may be modifiable through weight reduction." (PMID 40869064, 2025). "In obesity and metabolic syndrome, hyperinsulinemia is often a compensatory response to decreased sensitivity of peripheral tissues to insulin, leading to excessive insulin production and secretion by pancreatic β-cells." (PMID 40453670, 2025). "Nonetheless, we acknowledge substantial differences in methodology and population characteristics, including the unique RCT design of our study involving women with obesity, the comprehensive adjustment for confounders in our models, and the earlier timing of fasting insulin measurements." (PMID 40646607, 2025). "We further investigated whether m6A levels in the identified DMRs correlate with clinical variables related to obesity, fat distribution and metabolic parameters of glucose and insulin metabolism." (PMID 41225618, 2025). "Low BMI may reflect malnutrition, while obesity and sarcopenia interact through complex pathophysiological mechanisms involving pro-inflammatory cytokines, oxidative stress, insulin resistance, and reduced physical activity." (PMID 40529136, 2025). "This study aimed to test patients with different clinical obesity phenotypes for duplications or deletions in key obesity-related genes and connect the results with the markers used to describe an obesity profile, like adiponectin, leptin, and insulin." (PMID 40429924, 2025).
Obesity (continued). "Our Boolean model also revealed that obesity leads to down-regulation of key circadian genes, Bmal1 and Clock, which may impact several metabolic processes, including glucose homeostasis and insulin response." (PMID 40924721, 2025). "Increasing evidence indicates that beyond classical systemic mechanisms, local crosstalk among skeletal muscle, various adipose depots, fascia, and bone plays a crucial role in orchestrating lipid partitioning, insulin sensitivity, and tissue remodeling in obesity and T2DM." (PMID 41002965, 2025). "Thus, GLP-1 through gastrointestinal tract (GIT) and neuronal regulation controls insulin secretion to control metabolism, such as glucose metabolism and obesity." (PMID 40592472, 2025). "Obstructive inflammation, oxidative stress, and other aspects of obesity could weaken the activation of the PI3K/Akt signaling pathway to create insulin resistance and visceral fat storage." (PMID 40218884, 2025). "This pathway contributes to ATP buffering through creatine kinase activity, and elevated creatine levels in our cohort — particularly in women with obesity — may reflect the high energy demands of pregnancy, most pronounced in the insulin-resistant state." (PMID 41202005, 2025). "VD is thought to enhance insulin secretion, receptor expression, and exocytosis, which may help counteract obesity-related insulin resistance and promote improved vasodilatory responses to insulin." (PMID 41439140, 2025). "In obesity, imprinted miRNAs can influence the development and function of adipose tissue, which is essential for storing fat, regulating energy balance, glucose metabolism, and insulin signalling pathways." (PMID 41361331, 2025). "Previous studies have demonstrated that Zbed6‐KO also protects against obesity and insulin sensitivity induced by high‐fat diets, suggesting that it may also attenuate obesity‐ or T2D‐induced muscle atrophy." (PMID 40464206, 2025). "In GPR119‐deficient NAFPD mice, terazosin failed to induce the beneficial effects observed in regular NAFPD mice, including improvements in obesity, hyperglycemia, and insulin sensitivity, as well as the increase of β‐cell functional gene expression in the pancreas." (PMID 39413003, 2025). "The link we identified between the mtDNAq-associated methylation site in SH3BP4 and various obesity-related outcomes, particularly those assessing insulin sensitivity and body fat composition, implies a potential role of mtDNAq-induced methylation in the etiology of obesity." (PMID 40355419, 2025). "Simultaneously, by modulating store-operated Ca2+ entry and mitochondrial buffering capacity, these compounds bolster insulin responsiveness, elevate energy expenditure and optimize lipid metabolism, underscoring their promise in battling obesity and metabolic syndrome." (PMID 40871490, 2025). "Moreover, the effects of antidepressants on metabolic indicators such as insulin sensitivity, lipid metabolism, and body fat distribution are also significant in the development of obesity." (PMID 40308634, 2025). "In a now classic study, it was found that germ-free mice were comparatively protected against diet-induced obesity and exhibited reduced adiposity, improved glucose tolerance, and enhanced insulin sensitivity, all linking the microbiome to obesity and metabolic syndrome." (PMID 39673174, 2025). "Accordingly, lack of endogenous IL‐1β signaling in mice during refeeding and obesity could reduce the concentration of insulin in plasma with consequent normalization of glucose metabolism and body weight gain." (PMID 39287080, 2025). "Maternal VAT, and particularly its change during pregnancy, may influence the fetal metabolic environment, impacting insulin availability and potentially fetal growth in healthy women with overweight or obesity." (PMID 40854967, 2025).
Obesity (continued). "Participants in the highest TyG index quartile showed statistically increased risk of VDD when compared with those in the lowest TyG index quartile after adjustments for age, sex, smoking, obesity, insulin therapy, hypoglycemic agents’ medication [OR 2.44; 95% CI 1.45–4.10; P < 0.001]." (PMID 38997409, 2024). "Citrus flavonoids, especially naringin, naringenin, nobiletin, and hesperidin, are well known to reverse obesity and related metabolic abnormalities through the regulation of lipid metabolism, improvement in insulin resistance, and suppression of inflammatory responses in adipose tissue." (PMID 38398818, 2024). "Future studies are required to address whether or how ADGRL1 function is regulated by glucose, insulin, leptin, and different diets in widely used mouse models of the metabolic syndrome such as db/db, ob/ob and diet-induced obesity models." (PMID 37712955, 2024). "The aetiology of obesity in T2DM is related to disturbances in the cellular insulin activity." (PMID 38274329, 2024). "In obesity, high resistin levels directly inhibit insulin-induced glucose uptake in adipocytes." (PMID 39335642, 2024). "In addition, a previous study found that CTRP6 knockdown improved insulin sensitivity and reduced diet-induced obesity in mice." (PMID 38791090, 2024). "Here, we simultaneously measured interstitial glucose concentrations using CGM as well as plasma glucose and insulin concentrations during an oral glucose tolerance test (OGTT) in individuals with overweight or obesity to calibrate personalized models of glucose-insulin dynamics." (PMID 38580749, 2024). "People with sedentary behavior have a 20% higher risk of suffering from noncommunicable disease, decreased insulin sensitivity, obesity or developing chronic diseases." (PMID 39392825, 2024). "Obesity can impair incretin responses, reducing insulin secretion and glucose tolerance." (PMID 39104999, 2024). "Meanwhile, Eubacterium eligens and Eubacterium siraeum have been associated with lower insulin secretion and increased HDL-cholesterol production, respectively, further supporting the hypothesized relationship between AMD and obesity." (PMID 39599758, 2024). "The results showed that the intake of VP in subjects with obesity and IR produced a smaller increase in concentrations of insulin, branched-chain amino acids and gluconeogenic amino acids and tended to upregulate the expression of exosomal microRNAs compared to the intake of AP." (PMID 39062958, 2024). "Oxidative stress is another component of both aging and obesity and may also contribute to alterations in insulin dynamics." (PMID 38473112, 2024). "In contrast, aldosterone deficiency in HFD fed mice neither prevent obesity nor alter insulin efficiency." (PMID 39087083, 2024). "On one hand, both GLUTs and insulin transcript levels are elevated in ob/ob mice compared to the control group, indicating that GLUTs protein expression is already impaired in long‐term obesity." (PMID 38174807, 2024). "Obesity induces metabolic disorders, chronic low-grade inflammatory status and hormone alterations (e.g., higher levels of leptin, insulin, androgen, estrogen), which could further impair ovarian folliculogenesis." (PMID 38455649, 2024). "Irisin improves obesity, inflammation, and dyslipidaemia; therefore, the direct insulin-sensitising actions illustrated above exist within a broader picture of overall metabolic improvement, which likely makes a significant additional contribution to the reduction in IR." (PMID 39040132, 2024). "Its actions, such as insulin effects, are impaired in obesity." (PMID 38399315, 2024). "The obesity rate was notably higher among workers engaged in or with a history of shift work, possibly due to disruptions in circadian rhythms and sleep-wake cycles, leading to abnormal lipid metabolism and insulin secretion disturbances." (PMID 38191357, 2024).
Obesity (continued). "Nevertheless, not all individuals who are obese are vulnerable to these conditions, as some “metabolically healthy obese” individuals exhibit normal insulin sensitivity despite being overweight, but unhealthy patients with obesity are mainly characterized by excessive visceral fat content." (PMID 39474255, 2024). "Adults with obesity and T2D are characterized by elevated plasma concentrations of glucagon compared with healthy individuals, suggesting a potential resistance of the pancreatic α-cells to insulin." (PMID 38087928, 2024). "Furthermore, LCM has demonstrated its ability to inhibit α-glucosidase and α-amylase, reduce postprandial blood glucose levels, and improve insulin sensitivity, thus proving its anti-obesity and glucose-lowering effects." (PMID 39201257, 2024). "As miR-6236 is secreted by ATMs, we hypothesized that ATM-derived miR-6236 regulates adipocyte insulin signaling during obesity in an ATM-extrinsic manner." (PMID 38918428, 2024). "A study showed that maintaining adequate potassium intake could regulate insulin secretion and carbohydrate metabolism, leading to the prevention of obesity and metabolic syndrome (MetS)." (PMID 38229053, 2024). "In obesity-related hypertension, there is clear evidence of an imbalance of the systems regulating blood pressure behavior and chronic low-grade inflammation, favoring decreased insulin sensitivity." (PMID 38606379, 2024). "Combination treatment in the presence of chronic HFHS feeding prevented adipose tissue mass gain and inhibited the development of obesity, exerted a robust effect on brain insulin sensitivity, and decreased the deposition of protein levels of Aβ, detected by the antibody 4G8." (PMID 39201705, 2024). "On the contrary, we have not found any major effect of U90926 deficiency in vivo in terms of weight gain and other obesity‐related phenotypes, such as fat accumulation, metabolic changes including plasma levels of glucose, TG, NEFA, and insulin, WAT histology, and adipogenesis molecular markers." (PMID 38171546, 2024). "Human studies suggest that elevated irisin levels could compensate for the abnormal metabolism and insulin sensitivity of individuals with obesity." (PMID 39640300, 2024). "In addition to their antioxidant functions, such as ROS scavenging and endogenous antioxidant defense improvement, flavonoids affect obesity and lipid metabolism, insulin and glucose metabolism, and hypertension, as well as the cardiovascular system." (PMID 38892574, 2024). "Therefore, activation of PPARγ in adipocyte by the thiazolidinedione (TZD) class of insulin-sensitizing drugs (TZDs) can improve obesity and insulin sensitivity." (PMID 38332049, 2024). "Furthermore, KA rectified many issues related to obesity, enhancing hepatic steatosis and insulin sensitivity." (PMID 38655315, 2024). "Consequently, we confirmed that chemerin deteriorates obesity and impairs insulin sensitivity through inhibiting the thermogenesis program of adipose tissue." (PMID 38933207, 2024). "Therefore, there is favorable potential for these treatments since metformin + bixin-rich annatto extract improved insulin sensitivity in the animals with obesity." (PMID 39338363, 2024). "In individuals living with obesity, insulin sensitivity was increased following 6 weeks of fasted exercise training, whereas in individuals living with T2D, greater improvements in HbA1c following 12-weeks of training was observed where exercise was undertaken after breakfast." (PMID 39570874, 2024). "STEP 2 evaluated weight loss in 1,210 individuals living with T2DM and overweight/obesity not treated with insulin (HbA1c 7–10%)." (PMID 38903652, 2024). "One study demonstrated that in patients living with obesity and T2DM, 18% weight loss achieved either by RYGB or caloric restriction resulted in similar improvements in insulin sensitivity and β-cell function, suggesting that metabolic improvements are weight-related." (PMID 38903652, 2024).